BRCA2 (BRCA2 DNA repair associated)
Diseases named in the same sentence as BRCA2 in open-access papers (continued):
Sharing a sentence is not in itself a finding about the gene and the disease.
tumor (continued). "Therapies are personalized and depend on several factors, including tumor subtype, tumor stage, genomic markers, patient age, general health, menopause status, and even the presence of mutations known as BRCA1 or BRCA2." (PMID 33202711, 2020). "BRCA1 and breast cancer 2 (BRCA2) are tumor suppressor genes that control aberrant cell proliferation and prevent tumor development." (PMID 33680920, 2020). "The tumor suppressor proteins encoded by the breast cancer genes BRCA1 and BRCA2 participate in the HR of double-strand DNA breaks." (PMID 31963730, 2020). "BRCA1/BRCA2 tumor testing by next-generation sequencing (NGS) can detect simultaneously both somatic and germline variants, allowing the identification of more patients with higher likelihood of benefiting from PARPi." (PMID 32850417, 2020). "Potentially actionable mutations detected from initial IDHWT tumours included EGFR, PTEN, BRCA1, BRCA2, ATM, and ATR." (PMID 32082376, 2019). "Significant anti-tumor efficacy was observed for the combination therapy in the DLD-1 BRCA2 -/- xenografts with tumor regressions noted across both treatment groups." (PMID 31618864, 2019). "It is not uncommon for tumor-suppressing factors to rely on a secondary mutation to initiate tumor development, and in fact, this trend is also observed in BRCA1, BRCA2, and RAD51C mutations." (PMID 31775907, 2019). "The tumor suppressor BRCA2 played a major role in regulation of RAD51-catalyzed homologous recombination." (PMID 31506496, 2019). "DNA alkylators, including chlorambucil, melphalan and nimustine, were also isolated in a previous screen and shown to be active in vivo against allografted BRCA2‐deleted mouse tumours." (PMID 31273933, 2019). "Contrastingly, aneuploidy and polyploidy were increased in Brca2-inactivated tumor cell lines derived from a mouse model of pancreatic ductular adenocarcinoma." (PMID 30930946, 2019). "For BRCA2 BC versus WT, univariate analysis showed that tumor grade, the expression of HER2, and E-cadherin were independent markers of BRCA2 status." (PMID 31307407, 2019). "The results showed that the high expression level of BRCA2 was associated with high tumor differentiation and small tumor diameter, and the low expression level of BRCA2 with low tumor differentiation and large tumor diameter." (PMID 31700821, 2019). "Whole body deletion of the mouse Palb2 gene results in early embryonic lethality similarly to the Brca1 and Brca2 knock-out animals, indicating that all three tumor suppressor gene products, Palb2, Brca1 and Brca2 are essential for embryonic viability." (PMID 31877165, 2019). "When homologous recombination repair defects present in tumor cells (such as BRCA1 and BRCA2 mutations) that make DSB damage unrepairable, PARP inhibitors and homologous recombination repair defects react in the lethal synthesis of tumor cells." (PMID 31775908, 2019). "Proteins encoded by these three tumor susceptibility genes (PALB2, BRCA1, BRCA2) cooperate in the BRCA pathway by forming a complex, which is essential for HR repair." (PMID 31877165, 2019). "Chlorambucil inhibited specifically the growth of BRCA2‐deficient spheroids established from DLD1 cells, indicative of its potential use in a tumour setting." (PMID 31273933, 2019). "The tumor suppressor BRCA2 is positioned to influence both of these outcomes, and thereby influence genomic integrity, during meiotic and mitotic cell cycles." (PMID 30930946, 2019). "The three tumor samples (P26, P28, P29) had homozygous pathogenic variants in either BRCA1 or BRCA2 based on variant frequencies, indicating LOH in these samples." (PMID 31029168, 2019).
tumor (continued). "The best-known disease-associated examples of defective components of homologous recombination repair are the breast- and ovarian-associated tumor suppressor genes BRCA1 and BRCA2." (PMID 30684955, 2019). "In this GBM cohort, amongst the BRCA2 variants were confirmed somatic mutations in haemangioblastoma (BRCA2 : COSM3753648, COSM5019704), which is a rare, benign tumour that typically occurs in the cerebellum." (PMID 32082376, 2019). "Both BRCA1 and BRCA2 are tumour suppressor genes, and their functioning proteins have major roles in DNA double-strand break repair through homologous recombination (HR)." (PMID 31064392, 2019). "After correcting the size of the genome in each tumor to account for copy number alterations, we find that the BRCA1-mutated samples have larger genomes than BRCA2-mutated or sporadic tumors (Wilcoxon test p = 3.2 × 10− 3)." (PMID 31182087, 2019). "BRCA2 tumor suppressor plays key roles in cell physiology by promoting DNA replication and DNA double-strand breaks (DSBs) repair via homologous recombination." (PMID 31316060, 2019). "We further used BRCA2−/− HCT116‐derived tumours to compare the anti‐tumoral effects of cisplatin, chlorambucil and the PARP inhibitor talazoparib." (PMID 31273933, 2019). "Palb2-, Brca1- or Brca2- deleted tumor cells exhibit dramatically elevated sensitivity to DNA damaging drugs compared to KPC cells in vitro." (PMID 31877165, 2019). "On the otherhand, BRCA2 tumors are less homogeneous, but exhibit a higher score for tubuleformation, higher proportion of the tumor perimeter with a continuous pushingmargin, and a lower mitotic count than sporadic BCs." (PMID 31067289, 2019). "BRCA1 and BRCA2 are two genes involved in homologous recombination (HR)-mediated repair of DNA double strand breaks and have first been described as tumor suppressor genes in hereditary breast cancer." (PMID 31549213, 2019). "Five pathogenic/likely pathogenic alterations (BRCA1 n = 4 and BRCA2 n = 1) and three VUS in BRCA1 were detected in the tumor specimens only and were considered somatic mutations." (PMID 31653094, 2019). "This analysis resulted in an estimated power of 0.27 when comparing BRCA2 tumours to normal tissues and of 0.16 when comparing BRCA2 tumours to sporadic ones." (PMID 31182087, 2019). "To further investigate the therapeutic potential of chlorambucil, we tested its effect in cell lines established from BRCA2‐compromised human tumours." (PMID 31273933, 2019). "Because chlorambucil and cisplatin are equally effective inhibitors of BRCA2‐compromised tumours, our results indicate that chlorambucil has a higher therapeutic index than cisplatin in targeting BRCA‐deficient tumours." (PMID 31273933, 2019). "Of note is that BRCA2 overexpression was unable to fully restore HCC tumor cell growth following USP21 knockdown." (PMID 29706623, 2018). "As a consequence, the fraction of patients with BRCA2 homozygous deletion detected here (1.38%, 3/217) was lower than previously reported from two studies analyzing tumor tissue from metastatic patients (2.67%, 4/150 and 4.54%, 5/110)." (PMID 30458854, 2018). "The BRCA1 and BRCA2 genes are tumor-suppressor genes and involved in DNA damage repair and recombination, cell-cycle checkpoint control, apoptosis and transcriptional regulation." (PMID 30186165, 2018).
tumor (continued). "Meanwhile, miR-1245 expression was reduced in tumor tissues obtained from mice in hsa_circ_0046264 overexpression group, and the mRNA and protein expressions of BRCA2 were elevated." (PMID 29891014, 2018). "PCAT1 induces cell proliferation in vitro and functions as a transcriptional repressor by regulating a broad range of genes, including known tumor suppressor genes such as BRCA2." (PMID 29861844, 2018). "BRCA1 and BRCA2 are two well-characterised tumour suppressor genes involved in DSB repair by homologous recombination." (PMID 30060743, 2018). "BRCA1 and BRCA2 breast tumor suppressor proteins play important roles in DNA damage response and repair, maintenance of genome stability and tumor suppression." (PMID 29718910, 2018). "And, smMIPS sequencing has also recently been applied clinically to test for mutations in the tumor suppressor genes BRCA1 and BRCA2 and has demonstrated superior accuracy and turnaround time relative to previous laboratory‐developed testing." (PMID 29739035, 2018). "In contrast, BRCA1 and BRCA2 were expressed in both the cytoplasm and the nuclei of the tumor cells." (PMID 29784019, 2018). "Mutations in BRCA1 or BRCA2, homologous recombination deficiency (HRD), and platinum sensitivity were associated with tumor response." (PMID 29313279, 2018). "HR was first identified as a tumor suppressor pathway when RAD51 was found to associate with BRCA1 and BRCA2." (PMID 31435521, 2018). "PARP1-positivity was significantly associated with sex of patients (P = 0.038), higher tumor stage (P = 0.024), higher histologic grade (P = 0.008), and the expression of γH2AX (P = 0.001), BRCA1 (P = 0.009), and BRCA2 (P = 0.001)." (PMID 29784019, 2018). "Like BRCA2- and CHEK2-associated tumours, ATM-associated tumours are mostly luminal tumours but they do not show a particular histological subtype as observed in BRCA1- (medullary), BRCA2- (lobular), CDH1- (lobular), and PTEN-associated tumours (apocrine)." (PMID 29665859, 2018). "Genomic studies suggest that a subset of OS, including OS tumour cell lines (TCLs), exhibit genomic loss of heterozygosity (LOH) patterns reminiscent of BRCA1 or BRCA2 mutant tumours." (PMID 30006631, 2018). "We show that the human tumor suppressor BRCA2 interacts with RNAPII to regulate PPP release, thereby preventing unscheduled RNA-DNA hybrids (R-loops) implicated in genomic instability and carcinogenesis." (PMID 29386125, 2018). "Our data define two functions for the tumor suppressor and HR mediator protein, BRCA2, in RAD51 filament assembly." (PMID 29309696, 2018). "Mechanistically, we show that loss of USP21 in HCC cell lines results in a reduction of BRCA2, increased DNA damage accumulation and a concomitant tumor growth defect that partially depends on BRCA2." (PMID 28743957, 2017). "The likely evolutionary advantage of mutations or loss of BRCA2 and ATM in CRPC is that they act as tumour suppressors in the CRPC." (PMID 28851861, 2017). "Their study demonstrated that localized castration-sensitive BRCA2-mutant tumours are uniquely aggressive due to de novo aberration in genes usually associated with metastatic CRPC disease, justifying aggressive initial treatment." (PMID 29262604, 2017). "Our novel method enables reliable assessment of the tumor DNA mutation status of BRCA1 and BRCA2 in FFPE material derived from OCs." (PMID 27767231, 2017). "In BR28, for example, relatively high frequencies of EGFR p.R521K and PTCH1 p.T1195S over ATM p.H1380Y, BRCA2 p.N289H, and BRCA2 p.N991D were observed in plasma compared to tumor tissue data, indicating tumor heterogeneity." (PMID 29156805, 2017). "Here the authors show that USP21 regulates the ability of tumor cells to repair damaged DNA by regulating BRCA2 stability." (PMID 28743957, 2017). "Analysis of methylation patterns within the BRCA2 subgroup of tumours showed two clusters with correlation coefficients >0.8)." (PMID 28893223, 2017).
tumor (continued). "Together, these findings support the notion that USP21 promotes BRCA2 stability and protects from DNA damage accumulation in BRCA2-proficient tumor cells, which can in turn contribute to increased tumor growth and, ultimately, a more malignant phenotype." (PMID 28743957, 2017). "Consistent with the in vitro activities observed, CX-5461 exhibited a wide therapeutic index of activity in BRCA2 knockout tumour cells in xenograft models, when compared with isogenic wild type control cells." (PMID 28211448, 2017). "Sequencing of BRCA1 and BRCA2 using tumor‐derived DNA is hampered by the complexity of these genes, the low quality of the DNA derived from formalin‐fixed, paraffin‐embedded (FFPE) tumor samples and the low percentage of neoplastic cells in these samples." (PMID 27767231, 2017). "The analysis of DMD genetic alterations revealed a high frequency of gene mutations, which was similar to other well-known tumor suppressor genes (BRCA1, BRCA2, PTEN, RB1)." (PMID 27391342, 2017). "Spontaneous base substitution mutation rates increased sevenfold upon the disruption of either BRCA1 or BRCA2, and the arising mutation spectra showed strong and specific correlation with a mutation signature associated with BRCA1/2 mutant tumours." (PMID 27452521, 2017). "Initial studies focused solely on BRCA2 mutations, but have now evolved into whole genome sequencing (WGS) of tumours in patients with PDAC." (PMID 29069866, 2017). "As a consequence, CX-5461 greatly extended the survival time of the mice bearing tumours derived from BRCA2 knockout cells." (PMID 28211448, 2017). "Two independent tumor subclones were present at a CCF of ~50% each at day 0, with a BRCA2 V2620fs mutation, representing the surviving subclone, which also possessed a TSC2 P670S mutation, giving rise to subsequent samples." (PMID 29093439, 2017). "Due to the extended biological heterogeneity observed in HCC, it will, however, be important to determine to what extent USP21 and/or BRCA2 affect tumor growth across genetically distinct HCC subgroups." (PMID 28743957, 2017). "Ten out of 14 unstable tumours fell within the top quintile of the BRCA signature which was associated with deleterious mutations of BRCA1 (n = 2), BRCA2 (n = 7), and PALB2 (n = 2)." (PMID 29069866, 2017). "In HR-proficient tumours, synthetic lethality can also be induced by combining PARP1-i with a local treatment of mild hyperthermia, which causes degradation of BRCA2 for several hours and thereby HR deficiency at the heated tumour site." (PMID 28427225, 2017). "Much research has focused on the connected roles of BRCA1 and BRCA2 in HR, suggesting that impaired HR in their absence leads to genome instability that accelerates tumour development." (PMID 27452521, 2017). "BRCA2 or IHC features, and therefore concurrent review of BRCA1/2 mutational screening together with tumor markers have rarely been reported." (PMID 27478808, 2016). "These critical functions of BRCA2 are key to its ability to maintain the genomic integrity and contribute to its role as a tumor suppressor." (PMID 27490902, 2016). "PALB2 mediates interactions between BRCA1 and BRCA2 proteins, acts as a scaffold connecting numerous tumor suppressors, stimulates Polη-dependent DNA synthesis and RAD51 recombinase activity." (PMID 27434671, 2016). "We predict binding sites on the presynaptic filament for two modules present in each BRC repeat of the BRCA2 tumour suppressor, a critical HR mediator." (PMID 27596592, 2016). "BRCA2 tumour-suppressor protein is well known for its role in DNA repair by homologous recombination (HR); assisting the loading of RAD51 recombinase at DNA double-strand breaks." (PMID 27628236, 2016). "Our data suggests that a potential therapeutic outcome of combined BRCA2 downregulation and olaparib treatment would be to prevent tumor spread and growth at secondary sites in the peritoneal cavity following surgical resection of primary tumors." (PMID 26959114, 2016).
tumor (continued). "Our in vivo data suggest that it is possible to combine BRCA2 inhibition and olaparib treatment to reduce tumor burden in animals." (PMID 26959114, 2016). "Among tumours with ER, PR and HER2 data, 96.7 % were ER+, 86.8 % were PR+ and 83.4 % were HER2− in BRCA2 mutation carriers, vs. 90.3 % ER+, 78.6 % PR+ and 89.5 % HER2− in BRCA1 mutation carriers." (PMID 26857456, 2016). "Another study revealed, that FBN-1 expression is stimulated by Aurora A, a serine/treonine kinase, and is inhibited by tumour suppressor gene BRCA2." (PMID 27487789, 2016). "This indicates tumor suppression according to Knudson ́s two hit model, analogous to that of BRCA1/BRCA2 mutation carrier tumors." (PMID 26820313, 2016). "Database review from two institutions identified 46 tumor samples from patients with germline BRCA1 mutations and 35 tumor samples from patients with germline BRCA2 mutations from 1995 to 2013 with available tissue for immunohistochemistry (IHC) staining." (PMID 27708239, 2016). "BRCA2 is a multifunctional tumor suppressor involved in homologous recombination (HR), mitotic checkpoint regulation, and telomere homeostasis." (PMID 27761361, 2016). "It has been reported that inhibition of RAD52 either by specific shRNA or a small peptide aptamer induced synthetic lethality in tumor cell lines carrying BRCA1 and BRCA2 inactivating mutations." (PMID 26784987, 2016). "Although originally developed as chemosensitisers, these compounds induce synthetic lethality in tumour cells from patients carrying germline loss-of-function mutations in DNA damage pathway tumour suppressor genes BRCA1 and BRCA2." (PMID 27702751, 2016). "This increased tumor predisposition of Brca2G25R/KO mice suggests that the physical interaction of BRCA2 with PALB2 is critical for their tumor suppressor function." (PMID 27490902, 2016). "Functional characterization of these mice unequivocally demonstrates the importance of BRCA2-PALB2 interaction on BRCA2-mediated genome stability as well as tumor suppression." (PMID 27490902, 2016). "It is well established that BRCA1 and BRCA2 function as tumour suppressors by maintaining genomic integrity." (PMID 27498558, 2016). "Acquired chemotherapy resistance is mainly associated with the inactivation of tumour suppressors such as RB1, NF1, RAD51B and PTEN, germline BRCA1 or BRCA2 mutations, loss of BRCA1 promoter methylation, and overexpression of the drug efflux pump MDR12." (PMID 27833130, 2016). "PALB2 is a tumor suppressor and binding partner of BRCA2 that facilitates the nuclear localization and HR capabilities of BRCA2." (PMID 27642590, 2016). "BRCA2 is a tumour suppressor gene involved in deoxyribonucleic (DNA) repair via homologous recombination." (PMID 27488020, 2016). "FOXO3 methylation levels were significantly higher in BRCA1-mutated tumours compared with BRCA2, BRCAx (non-BRCA1/2) and non-BRCA1-mutated (BRCA2/x) tumours." (PMID 27043660, 2016). "The tumor suppressor genes BRCA1 and BRCA2, which were both up-regulated in bats, encode proteins that are pivotal in maintaining genomic stability by promoting efficient and accurate repair of DNA double-strand breaks." (PMID 27832764, 2016). "To mimic a heterogeneous tumor cell population that is predominantly HRR-deficient, we co-cultured SKOV-3shBRCA2 (low BRCA2) and SKOV-3shcontrol (high BRCA2) in a 3:1 ratio." (PMID 26959114, 2016). "Analytical sensitivity for detection of germline copy number changes in BRCA1 and BRCA2 genes in normal, tumour and ascites samples—concordance between MLPA and results from the MLPA-seq." (PMID 26569395, 2015).